ENSG00000252682
Synonyms: LOC124904806
Gene: Small nucleolar RNA gene on chromosome 1 (154,288,460 to 154,288,527, forward strand). Ensembl gene ENSG00000252682.
Gene Ontology:
Biological process: RNA processing
Cellular component: nucleolus
Homologues: Paralogues in human: SNORD59A (71% identical).